TYR (tyrosinase)
Diseases named in the same sentence as TYR in open-access papers (continued):
Sharing a sentence is not in itself a finding about the gene and the disease.
melanoma (continued). "The presence of tyrosinase messenger RNA (mRNA) in the blood is assumed to indicate melanoma metastases." (PMID 31717496, 2019). "Clinical responses were retrospectively observed in patients with stage III and IV melanoma that were treated with ipilimumab upon disease progression, after receiving at least 3 bi-weekly vaccinations with gp100 and tyrosinase-loaded DCs." (PMID 31020037, 2019). "In the human skin cells, tyrosinase is the only rate-limiting enzyme for melanogenesis and the expression of tyrosinase has physiological functions in the process of melanoma’s occurrence and development." (PMID 31072148, 2019). "The significant reduction in melanin synthesis was mainly due to a dose-dependent inhibition of tyrosinase activity and protein expression associated with tyrosinase and melanocyte inducing transcription factor (MITF) in A375 melanoma cells." (PMID 31083417, 2019). "The melanin content and cellular tyrosinase activity of α-MSH-stimulated B16F10 melanoma cells were evaluated." (PMID 30695994, 2019). "LEF1 is an outstanding candidate gene for melanoma susceptibility as it can regulate microphthalmia-associated transcription factor, KIT-ligand (KITLG), tyrosinase, and other melanogenic genes." (PMID 30744341, 2019). "Its role as a tyrosinase substrate also makes 4-HA a promising agent to treat melanoma, since 4-HA can be oxidized to 4-methoxycatechol and its o-quinone." (PMID 31261793, 2019). "After the post-Golgi stage, linoleic acid induces the proteasomal degradation of tyrosinase via post-translation alteration in the endoplasmic reticulum in melanoma cells." (PMID 30224716, 2018). "Melanoma antigens, including Melan-A, tyrosinase, and gp-100, were strongly expressed at the RNA level." (PMID 29750176, 2018). "In conclusion, the results from the current study suggest that the enzyme-based assay using murine tyrosinase from B16-F10 melanoma cells is more appropriate than the mushroom tyrosinase for screening of natural compounds with potential whitening effects." (PMID 29890751, 2018). "Melanoma cell differentiation is generally accepted to be related to inhibition of cell proliferation, dendritic-like morphology, increased tyrosinase activity, and melanin production." (PMID 30115883, 2018). "In the present study, we evaluated a more lipophilic derivative, 2-S-lipoyl caffeic acid methyl ester (LCAME), as an inhibitor of tyrosinase from human melanoma cells." (PMID 30042336, 2018). "A specific biomarker of melanoma is tyrosinase, the rate-limiting enzyme required for the biosynthesis of melanin by melanocytes." (PMID 30441769, 2018). "The observed PEE inhibitory activities on both tyrosinase and melanoma pigmentation indicate skin whitening properties." (PMID 29320400, 2018). "Here, in addition, we describe a novel activity of the HSP90 inhibitor 17-AAG which induces melanization in BRAFWT melanoma cells in a tyrosinase-independent manner while increasing expression of accessory melanogenic enzymes and tumor antigens TYRP1 and DCT." (PMID 29481571, 2018). "Tyrosinase inhibitory activity was also evaluated in B16F10 murine melanoma cells, showing that MHY1498 was effective at preventing α-melanocyte-stimulating hormone (α-MSH)-induced melanogenesis." (PMID 30551624, 2018). "Normally, B16F10 melanoma cells increase melanin production, tyrosinase activity, and tyrosinase protein expression in response to UVA." (PMID 29734688, 2018). "As an underlying mechanism of 1c mediated anti-melanogenic effect, we investigated the inhibitory activity against melanin contents and cellular tyrosinase in B16F10 melanoma cells." (PMID 30360412, 2018). "The detectable tyrosinase activity is unique among animal amelanotic melanomas making the Ab line similar to human amelanotic forms expressing tyrosinase activity." (PMID 29614755, 2018).
melanoma (continued). "PEE modulatory effects on skin melanization were evaluated in free solution on mushroom tyrosinase using l-tyrosine as a substrate, as well as on MeWo melanoma cells growing in vitro." (PMID 29320400, 2018). "In conclusion, our study demonstrated that finasteride inhibited melanogenesis in melanocytes and melanoma cells through the down-regulation of tyrosinase, TRP-1, MITF and adenylate cyclase expression." (PMID 29397551, 2018). "N. sintenisii extracts inhibited cellular melanin biosynthesis and tyrosinase activity in B16F10 murine melanoma cells and decreased MITF level." (PMID 29755554, 2018). "On this basis, in the present study we examined the ability of LCA to inhibit tyrosinase from HBL human melanoma cells." (PMID 30042336, 2018). "In this study, the biological activity of sorghum ethanolic extract on α-melanocyte-stimulating hormone (α-MSH)-induced TYR expression was evaluated in B16F10 melanoma cells." (PMID 29865165, 2018). "Here, resveratrol also downregulated melanogenesis-related proteins such as tyrosinase, tyrosinase related protein (TRYP) 1, TRYP2 and microphthalmia-associated transcription factor (MITF) in melanoma cells." (PMID 29522491, 2018). "MEK inhibition has previously been shown to increase melanogenic gene expression, including tyrosinase expression, in immortalized murine melanocytes, and tyrosinase gene and protein expression in B16 murine melanoma cells." (PMID 29481571, 2018). "Data obtained with mushroom tyrosinase were confirmed by experiments on melanoma cells, showing an about 50% reduction of melanin content induced by 50 μg/mL PEE at 72 h." (PMID 29320400, 2018). "For example, cells of a melanoma clone (wild type for tyrosinase, C/C) were implanted into BALB/c nu/nu mice (homozygous mutation for albino tyrosinase, c/c)." (PMID 31069316, 2018). "Previous studies have reported that NAOSs with different DPs, including neoagarobiose (NeoDP2), neoagarotetraose (NeoDP4) and neoagarohexaose (NeoDP6), had a whitening effect and inhibited TYR activity in murine melanoma B16F10 cells." (PMID 30469402, 2018). "Uro-A and Uro-B were found to suppress tyrosinase activity and to attenuate melanogenesis in B16 melanoma cells." (PMID 30441769, 2018). "B16F10 melanoma cells pretreated with caffeic acid, ferulic acid, quercetin, rutin, and avobenzone display inhibited melanin production and tyrosinase activity." (PMID 29734688, 2018). "Catethins, the main components of PN3, have been proven to inhibit melanin synthesis by downregulating the expression of tyrosinase in B16 melanoma cells." (PMID 29385729, 2018). "In primary human epidermal melanocytes (HEMn) and B16F10 melanoma cells, Nrf2 inhibits melanogenesis and tyrosinase protein expression." (PMID 29734688, 2018). "Extracts of Ishige okamurae Yendo inhibited mushroom TYR activity and melanin synthesis in murine melanoma B16F10 cells." (PMID 30469402, 2018). "Immunotherapeutic approaches have been investigated using T cells to target melanoma-associated antigens (MAA – Mart-1, tyrosinase, gp100)." (PMID 29175861, 2018). "PEE induced dose-dependent mushroom tyrosinase inhibition, up to about 45% inhibition at 1000 μg/mL, while 50% reduction of melanin was observed in melanoma cells exposed to 50 μg/mL PEE." (PMID 29320400, 2018). "A first Phase I pilot veterinary trial exploiting the safety and the anti-tumor potential of a xenogeneic DNA vaccine coding for the human tyrosinase in dogs affected by advanced malignant melanoma was conducted in 2003 by Bergman and collaborators." (PMID 29534457, 2018). "It differed from the parental Ma melanoma in its higher tyrosinase activity, lower pigmentation level, ability to produce pheomelanin, and slightly slower growth rate, with other parameters similar to the Ma melanoma." (PMID 29614755, 2018). "Suppression of tyrosinase activity in the cultured B16F10 melanoma cells was occurred after treatment of the cells with 50 μg/mL of all extracts with different ratios." (PMID 29755554, 2018).
melanoma (continued). "The inhibition of mushroom tyrosinase was then compared to the inhibition of crude murine tyrosinase extracted from B16-F10 melanoma cells." (PMID 29890751, 2018). "Tyrosinase inhibitor is anticipated to provide new therapy to prevent skin pigmentation, melanoma and neurodegenerative diseases." (PMID 29383286, 2018). "Numerous studies have found that upregulation of melanogenesis is often observed in malignant melanoma with overexpressed tyrosinase levels in blood as well as tumor tissues." (PMID 30249988, 2018). "To determine the mechanism underlying the inhibitory effect of the ES extract on melanogenesis, we assessed the intracellular tyrosinase activity in B16F10 melanoma cells." (PMID 30223806, 2018). "TyR is a vital enzyme that controls the production of melanin, and can be used as a highly selective indicator to monitor melanoma stages." (PMID 30096895, 2018). "Alternatively, endosomal/lysosomal degradation of tyrosinase was accounted in inulavosin-treated melanoma cells." (PMID 30224716, 2018). "The most obvious advantage of this model is that it expresses murine homologs of the melanoma differentiation antigens (tyrosinase, gp100, MART-1, TRP-1, and TRP-2)." (PMID 29276510, 2017). "The study evaluated the potential of chlorogenic acid to be used as a hyperpigmentation-correcting ingredient based on its ability to inhibit tyrosinase activity in B16 melanoma cells." (PMID 28208818, 2017). "The roles of pigmentation in melanoma can be paradoxical: elevated tyrosinase expression can induce an auto-immune response leading to metastatic regression." (PMID 28265786, 2017). "Tyrosinase, which plays an essential role in melanin synthesis and melanocyte differentiation, has been used as a melanoma biomarker for disease detection purposes." (PMID 28567163, 2017). "In particular, phlorotannins have been studied as tyrosinase inhibitors in melanoma cells although the intent of the studies was to identify skin lightening compounds in seaweeds, rather than to act against melanoma tumors." (PMID 28458463, 2017). "They suggested that fucoidan upregulated TYR expression, which was positively correlated to its apoptosis-stimulating activity in melanoma cells." (PMID 28946635, 2017). "B16F10 murine melanoma cells treated with pratol showed a significantly increased expression of tyrosinase, TRP-1, and TRP-2." (PMID 29019920, 2017). "On the other hand, geoditin A at sublethal doses (≤5.0 μg·mL−1) decreased melanogenesis and glycosylation of tyrosinase (TYR) in murine B16F10 melanoma cells (CRL6475, ATCC) in a dose-dependent manner, but ROS- and MITF- in an independent one." (PMID 28134844, 2017). "Inhibition of melanogenesis by tyrosinase inhibitors sensitized melanoma cells towards cytotoxic action of chemotherapeutic agents or immunotoxic activities of IL-2 activated lymphocytes." (PMID 29045474, 2017). "Western blot analysis revealed that 10-HDA inhibited the activity of tyrosinase and the expression of tyrosinase-related protein 1 (TRP-1), TRP-2, and microphthalmia-associated transcription factor (MITF) in B16F1 melanoma cells." (PMID 28793915, 2017). "We confirmed, using western blot and spectrophotometry, that Hsp90 or BRAF inhibitor-induced melanoma cell differentiation resulted in an upregulation of tyrosinase and melanin expression levels, in comparison to control cells." (PMID 28811486, 2017). "Tumor-specific lymphocytes that target malignant cells through recognition of tumor-associated antigens—such as tyrosinase, Melan-A/MART-1, gp100, TRP-1, and TRP-2—have been isolated from melanoma." (PMID 28690979, 2017). "Current study followed a set of experiments on B16-F10 mouse melanoma cell model with a focus on tyrosinase activity and production." (PMID 28872626, 2017). "For example, the promoters of tyrosinase or survivin genes that are over-expressed in melanoma, have been incorporated into virus genomes and used for the oncospecific targeting of engineered OVs." (PMID 28567163, 2017).
melanoma (continued). "It has been demonstrated that incorporation of tyrosinase promoter to drive the expression of the viral genes of adenovirus leads to an obvious melanoma-selective viral cytotoxicity." (PMID 28567163, 2017). "The cell-based assay using B16F10 melanoma cells confirmed that the compounds inhibit mammalian tyrosinase." (PMID 29283382, 2017). "Ethosomes also exhibited the higher tyrosinase inhibition activity as well as the reduction of melatonin content in comparison to other formulations in B16 melanoma cells." (PMID 28804723, 2017). "Because upregulation of melanogenesis is often observed in malignant melanoma with overexpressed tyrosinase levels in blood as well as tumor tissues, it is apparent that melanogenesis is a potential target for chemotherapy of malignant melanomas." (PMID 28165370, 2017). "Tyrosinase is essential for pigment synthesis in melanocytes and is an established antigen in melanoma." (PMID 28265786, 2017). "Conversely, miR-211, a known transcriptional target of MITF, is induced in melanotic melanoma cells, where it targets EDEM1 and consequently impairs the degradation of TYROSINASE (TYR) through the ER-associated degradation (ERAD) pathway." (PMID 28445987, 2017). "To address this question, we flow-sorted murine TRP-1 CD4+ T cells, which express a transgenic TCR specific for tyrosinase on melanoma, via CD26 expression." (PMID 29213079, 2017). "Isolates 141–146 were found to exhibited stronger activate abilities of melanogenesis and tyrosinase in B16 melanoma cells than those of positive control (8-MOP) at 50 μmol/L." (PMID 28777326, 2017). "The TAAs of tumor types such as melanoma (gp100, Melan-A/Mart-1, tyrosinase,MAGE-1),prostate cancer (PSA,PSCA), etc. are known." (PMID 29104773, 2017). "The RNA encoded for the melanoma antigens NY-ESO-1, MAGE-A3, tyrosinase, and TPTE (transmembrane phosphatase with tensin homology) and resulted in IFNα and antigen-specific T cell responses in all three patients." (PMID 29276510, 2017). "Despite melanoma has been viewed as a complex disease, the inhibition of tyrosinase is the most common pathway to achieve skin whiteness as it is the key enzyme that catalyzes the rate-limiting step of melanin biosynthesis." (PMID 29197358, 2017). "The application of tyrosinase promoter controlled CD95L has been shown to selectively induce apoptosis in melanoma cells while sparing the non-melanoma cells." (PMID 28567163, 2017). "Melanin content and tyrosinase activity are primary molecular markers of melanoma cells differentiation." (PMID 29245919, 2017). "Consistently, ethosomes exhibited higher tyrosinase inhibition activity and melanin content reduction when compared to other formulations in B16 melanoma cells." (PMID 28804723, 2017). "Later, the effect of chloroform extract of the plant on melanogenesisin murine B16-F0 melanoma was studied as well by the same group, and a concentration-dependent stimulation effect on tyrosinase and melanogenesis was observed." (PMID 28777326, 2017). "We measured the potential cytotoxic properties of the extracts as well as their ability to alter tyrosinase activity in B16F10 melanoma cells." (PMID 28333105, 2017). "Kojic acid is a kind of melanoma specific inhibitor, it changes the three-dimensional structure of tyrosinase and prevents tyrosinase activation, and then inhibits the formation of melanin." (PMID 28915638, 2017). "In contrast, a recent study had no inhibitory effects of fucoidan, isolated from the same alga, on TYR, TRP1, TRP2 and MITF expression in B16 murine melanoma cells, although it inhibited cellular melanin and TYR activity." (PMID 28946635, 2017). "In fact, this type of activity has been demonstrated previously with a high-affinity melanoma antigen tyrosinase-reactive TCR expressed by CD4+ T cells." (PMID 29123516, 2017).
melanoma (continued). "In mouse melanoma cells miR-211 acts by increasing the mRNA and subsequently protein levels of Tyrosinase (Tyr) and Tyrosinase-Related Protein 1 (Tyrp1), two enzymes involved the biosynthesis of melanin pigment." (PMID 28445987, 2017). "Certain tumor antigens, such as tyrosinase and melanoma–associated antigen (MAGE) in melanoma, are therefore used as the biomarkers for diagnostic test or the development of cancer therapies." (PMID 28567163, 2017). "Melanoma cells treated using these agents are known to exhibit increased levels of melanin pigment and tyrosinase activity." (PMID 28811486, 2017). "Some studies on the activity of tyrosinase from human malignant melanoma cells demonstrate that α-arbutin is more potent than β-arbutin as an inhibitor of the enzyme." (PMID 28493937, 2017). "The melanin content was quantified in B16 melanoma cells; after a 48-h exposure to phenolic acid at 500 μM, the melanin levels were suppressed due to a decrease in tyrosinase activity." (PMID 28208818, 2017). "In vivo particle-mediated gene gun delivery of the melanocyte-specific tyrosinase promoter containing plasmids pVAX1/Tyr-Cre and pVAX1/mTyr-Cre showed induction of melanomas (Tyr and mTyr 2/8), although with a lower efficiency than DNA tattoo administration." (PMID 27999416, 2016). "The results of the present study indicate that making this kind of distinction using standard melanoma-associated markers would be very difficult because MM127 cells cannot be identified using S100, Melan-A, HMB-45, MITF or tyrosinase." (PMID 27087056, 2016). "Specifically targeting melanocytes by using the tyrosinase promoter resulted in the sole formation of melanomas, which were responsive to selective BRAF inhibition." (PMID 27999416, 2016). "Stat3 activity increased melanoma invasiveness and is required for active melanogenesis by regulating tyrosinase gene expression and enzyme activity." (PMID 26830149, 2016). "Quercetin was reported to inhibit the formation of melanin in B16 melanoma through reduction of the intracellular activity of tyrosinase and protein expression." (PMID 26901191, 2016). "In pathological states such as melanoma, high levels of tyrosinase in the serum and in tissues promote the overproduction of melanin." (PMID 26805794, 2016). "In α-MSH-stimulated B16 melanoma cells, luteolin inhibited both tyrosinase activity and melanin production in a concentration-dependent manner." (PMID 27829416, 2016). "Melanocytes and melanoma cells, in particular, have a unique feature in that they specifically express the oxidative enzyme tyrosinase, which can oxidize quercetin into reactive adducts." (PMID 27843913, 2016). "The tyrosinase enzyme is highly active in melanoma cells and metabolizes polyphenolic compounds; tyrosinase expression thus makes feasible a target for polyphenol-based therapies." (PMID 27843913, 2016). "Melanoma develops from neural crest cells, which express tyrosinase – a key enzyme in the pigmentation pathway." (PMID 27843913, 2016). "Ganodermanondiol significantly inhibited tyrosinase activity, the expression of tyrosinase-related proteins, and microphthalmia-associated transcription factor (MITF) expression in B16F10 melanoma cells." (PMID 27801787, 2016). "Herein, we show that a large fraction of the human melanoma epitope tyrosinase reactive TCR transduced T cells that exhibit effector memory (TEM) phenotype and undergo programmed necrosis, or necroptosis, upon TCR restimulation." (PMID 27750220, 2016). "Quercetin, a popular flavonoid aglycone derived from various fruits and vegetables, is a potent melanogenesis and tyrosinase inhibitor in murine B16F10 melanoma cells." (PMID 27801787, 2016).